AXL (AXL receptor tyrosine kinase)
Diseases named in the same sentence as AXL in open-access papers (continued):
Sharing a sentence is not in itself a finding about the gene and the disease.
tumor (continued). "This is in contrast to tumor formation by MDA-MB-231 cells, a mesenchymal triple-negative cell line, where AXL was shown to be required for primary tumor formation, and knocking down AXL expression in established tumors reduces their size." (PMID 32148495, 2020). "The transient combination of the IGF-1R inhibitor with continuous osimertinib eradicated the tumor cells and prevented the regrowth in CDX and PDX models of AXL-low-expressing EGFR-mutated NSCLC." (PMID 32929081, 2020). "In various cancers, AXL is known to regulate the proliferation, survival, angiogenesis, invasion, and migration of tumor cells." (PMID 33374832, 2020). "Distinct AXL blockage impacts on tumour progression through immune surveillance by AXL-expressing immune cells and anti-proliferative effect on AXL-expressing tumour cells." (PMID 31822557, 2020). "Yet, the connection of AXL to PEAK1 was completely dispensable for rescuing tumor growth, demonstrating the importance of AXL/PEAK1 specifically in the invasion process." (PMID 32681075, 2020). "In summary, our data show that axl-148b influences mammosphere formation and growth in an AXL-dependent manner, suggesting the possibility to use this conjugate to block tumor cell stemness and subsequent metastatization." (PMID 32174798, 2020). "AXL expression is directly regulated by tumor suppressor miRNAs, such as miR-199a/b and miR-34a, and is closely associated with EMT in various types of cancer." (PMID 33374832, 2020). "AXL expression was detected in three of 12 (25%) and nine of 19 (47%) tumor specimens obtained before and after EGFR‐TKI treatment, respectively." (PMID 31419057, 2019). "Although tumor size in the vehicle-administered group was much larger, AXL expression was undetected in immunohistochemistry staining." (PMID 31043587, 2019). "AXL inhibition by SLC-391 decreased tumor growth and increased the ratio of M1/M2-polarized macrophages in a CT26 murine colon carcinoma model." (PMID 31694201, 2019). "Collectively, the combination of YD and EGFR-TKIs shows potential for both inhibitions of in vitro cell proliferation and in vivo tumor growth via AXL degradation." (PMID 31043587, 2019). "In the last year, there has been growing interest to further unravel the role of AXL in cancer cell biology and to combine it specifically with immune checkpoint inhibitors and/or chemotherapeutic agents to induce a proper anti-tumor response." (PMID 31694201, 2019). "Upregulation of AXL expression in tumor tissue was apparent after the development of EGFR‐TKI resistance in patients of the present study." (PMID 31419057, 2019). "Although tumor size in the vehicle-administered group was much bigger in long-term xenograft, the AXL expression was negligible." (PMID 31043587, 2019). "Expression of AXL in the cell cytoplasm of pre-EGFR-TKI-treated tumor samples was evaluated using immunohistochemistry (IHC) staining and scored as high (3+), intermediate (2+), low (1+), and no expression of AXL." (PMID 30651547, 2019). "Recuse assays further found that the tumour suppressive roles of LINC00526 were dependent on the repression of AXL." (PMID 31240814, 2019). "We investigate the ability of the novel siRNA delivery platform, p5RHH, to deliver anti-AXL siRNA (siAXL) to tumor cells both in vitro and in vivo as well as examine the phenotypic effects of this siRNA interference." (PMID 30886159, 2019). "The findings of the present research confirm the results of the recent studies about overexpression of GAS6 and AXL in tumor tissues." (PMID 31700829, 2019). "AXL expression was analyzed by western blotting using tumors sampled at 24 days after tumor implantation for the control group and at 108 days after administration for the erlotinib-treated group." (PMID 31497246, 2019). "In this study, we investigated the effect of DS-1205b, a novel and selective inhibitor of AXL, on tumor growth and resistance to EGFR TKIs." (PMID 31497246, 2019).
tumor (continued). "Mice that received both CARTs and AXL inhibitors rejected the tumor, while mice receiving only CARTs redeveloped MCL." (PMID 31694201, 2019). "We correspondingly observed a loss of E-cadherin expression and gain of N-cadherin, vimentin, and AXL expression in the acquired-resistant tumour for patient #4612." (PMID 31653970, 2019). "Cell-based assays showed that adding AXL inhibitors in tumor cell- or patient-derived xenograft models synergized with osimertinib by reducing the viability of osimertinib-treated NSCLC cells." (PMID 31266248, 2019). "Both miR-199a and miR-34a regulate the expression of oncogenic AXL; in contrast, tumor suppressor PPARγ induced miR-92b reduced AXL expression in fibroblasts." (PMID 31752264, 2019). "In hematological malignancies, the expression and function of AXL is highly diverse, not only between the different tumor types but also in the surrounding tumor microenvironment." (PMID 31694201, 2019). "The addition of an AXL inhibitor during either the initial or tolerant phases reduced tumor size and delayed tumor re-growth compared to osimertinib alone." (PMID 30651547, 2019). "Upregulation of the receptor tyrosine kinase AXL in tumor tissue has been detected in about one‐fifth of NSCLC patients with acquired resistance to EGFR‐TKIs." (PMID 31419057, 2019). "IHC of AXL expression in tumor specimens revealed that three of 12 (25%) pretreatment specimens and nine of 19 (47%) post‐treatment specimens were positive for AXL expression (H‐score of ≥1)." (PMID 31419057, 2019). "AXL positivity in tumor tissue after the development of EGFR‐TKI resistance was 50% (5/10) for T790M‐positive specimens and 50% (4/8) for T790M‐negative specimens." (PMID 31419057, 2019). "Stable knockdown of AXL also led to downregulation of the NF-κB pathway and reduced tumor formation in vivo." (PMID 31815659, 2019). "Functionally, AXL-driven mesenchymal characteristics endow tumor cells with an increased invasive phenotype and a resistance to chemotherapeutics." (PMID 31007848, 2019). "Although no patient showed high AXL expression (H‐score of >10) in pretreatment tumor specimens, three patients showed high AXL expression in post‐treatment tumor specimens." (PMID 31419057, 2019). "We also detected FGFR1 and AXL activation in tumor cells resulting from the communication with CAFs." (PMID 29946230, 2018). "Using an in vivo tumor xenograft mouse model, we demonstrated that targeting AXL with a low dose of R428 effectively sensitizes resistant cancer cells to epirubicin." (PMID 30353671, 2018). "The combination of AxL and growth arrest-specific gene 6 (Gas6) is responsible for tumor progression and migration." (PMID 30373180, 2018). "The co-localisation of AXL and PD-L1 in tumour infiltrating immune cells was determined using NeoGenomics MultiOmyx." (PMID 30400835, 2018). "Data from a tumor xenograft mouse model indicated that inhibition of AXL with R428 in combination with epirubicin synergistically suppresses tumor growth and proliferation." (PMID 30353671, 2018). "Here, we established that challenging conditions, such as serum deprivation, divide AXL‐overexpressing tumor cell lines into non‐self‐sustaining and self‐sustaining subtypes in 3D spheroid culture." (PMID 28675785, 2017). "Alternatively, GAS6 expressed by the tumor microenvironment was also shown to activate AXL in a paracrine manner." (PMID 28118606, 2017). "Cabozantinib is an orally bioavailable TKI which targets VEGF receptors (VEGFRs), MET, AXL, and other receptor tyrosine kinases involved in tumor development and progression through angiogenesis, anti-apoptosis, invasiveness, metastasis, and drug resistance." (PMID 28247252, 2017). "Taken together, we identify PROS1 as a driver of OSCC tumor growth and a modulator of AXL expression." (PMID 28118606, 2017).
tumor (continued). "Tumors inhibited for PROS1 expression were characterized by attenuated proliferation coupled with increased apoptotic foci, in agreement with AXL being a mediator of tumor cell survival." (PMID 28118606, 2017). "While all three TAM RTKs are expressed in CRC cells, AXL correlates with migration/invasion gene expression and the inhibition of AXL alone is sufficient to reduce tumor cell migration/invasion." (PMID 28727830, 2017). "Results revealed a punctate distribution of KISS1 and a robust localization of KISS1R and AXL in tumor cells." (PMID 28422142, 2017). "Studies have indicated that AXL overexpression and activation plays important roles in cell proliferation, migration, and invasion of tumor cells in many malignancies." (PMID 28455956, 2017). "Knockdown of AXL stimulated actin stress fibre formation, which inhibited tumour formation in a mouse xenograft model." (PMID 29259259, 2017). "Experiments in vitro with the cancer cell line, which was derived from this xenograft tumor, showed that the blockade of AXL and SMO, of SMO and EGFR, and, more efficiently, of AXL and EGFR was able to revert the resistance to EGFR." (PMID 28416737, 2017). "Together, the cumulative impact results in a feed-forward mechanism to increase AXL expression in tumor cells." (PMID 28118606, 2017). "Phosphoproteomic analyses of 41 NSCLC cell lines and 150 NSCLC tumours revealed that AXL phosphorylates tyrosine residues, similar to other oncogenic kinases such as EGFR, c-Met, and ALK31." (PMID 29259259, 2017). "Nevertheless, differential tumor uptake between 64Cu-anti-hAXL and isotype-matched IgG suggests that the former specifically bound to AXL-expressing tumor cells both in vitro and in vivo." (PMID 29097911, 2017). "Tumours that had resumed growth on BRAF inhibitor alone displayed a strong increase in AXL mRNA expression." (PMID 28606996, 2017). "17-AAG treatment caused significant decline in AXL expression in orthotopic TNBC MDA-MB-231 tumors, inhibited EMT, and delayed tumor growth in vivo, resulting in significant reduction in tumor uptake of 64Cu-anti-hAXL as clearly visualized by microPET/CT." (PMID 29097911, 2017). "Silencing AXL or the inhibition of AXL kinase activity significantly inhibits tumor cell migration and invasion." (PMID 28727830, 2017). "This tumor expressed higher levels of both phospho-AXL and SMO when treated with osimertinib, concomitantly with increased levels of vimentin and PDL-1." (PMID 28416737, 2017). "This survival pathway becomes important after treatment of this self‐sustaining tumor cells with AXL/MET inhibitor BMS777607 or multitargeted TKI sunitinib." (PMID 28675785, 2017). "Intriguingly, in xenografts, the BRAF inhibitor/bosentan combination treatment led to a significant suppression of EDNRA expression within the residual tumours, which correlates with the drop in AXL expression." (PMID 28606996, 2017). "Despite mandatory submission of tumour samples for all participants, only 11, 16 and 18/31 patients had sufficient tissue for genotyping, AXL and MET expression respectively." (PMID 29050231, 2017). "The expression of AXL was positively associated with GAS6 expression (P < 0.001), and tumor differentiation (P = 0.014) in advanced NSCLC with metastases." (PMID 28551766, 2017). "The immunohistochemistry (IHC) analyses of DU145-DR tumor specimens indicated that MP470 or docetaxel alone significantly inhibited the expression of AXL in DU145-DR xenografts." (PMID 28455956, 2017). "In these “progressed” tumours, nearly all cells stained positive for AXL, demonstrating that the number of AXL‐high cells had increased." (PMID 28606996, 2017). "The only single tumor resistant to afatinib plus cetuximab, and then refractory to both osimertinib and chemotherapy, showed AXL activation along with an increased expression of SMO after treatment with osimertinib." (PMID 28416737, 2017).
tumor (continued). "The IHC findings thus indicate that AXL gains importance during tumor progression and should also be evaluated as a therapeutic target in more advanced stages." (PMID 28025482, 2016). "In lung cancer, AXL plays an important role in the invasion of tumor cells, and its inhibition decreased tumor growth in xenograft models." (PMID 28025482, 2016). "With the generation of AXL deficient mice and the use of AXL inhibitors in immune competent tumor models, we will be able to better understand how GAS6/AXL signaling is utilized in tumor stromal crosstalk to promote tumor progression." (PMID 27834845, 2016). "Here we review the literature that has illuminated the cellular and molecular mechanisms by which AXL signaling promotes tumor progression and we will discuss the therapeutic potential of AXL inhibition for cancer therapy." (PMID 27834845, 2016). "Tumor cell motility is impaired in SF126 AXL-DN cells, which indicates that these cells are unable to invade normal brain tissue." (PMID 26848524, 2016). "To evaluate the contribution of AXL to tumor cell invasion, we performed matrigel invasion assays and found that AXL-deficient ARK 1 and Hec50a cells were significantly less invasive than controls." (PMID 27764792, 2016). "Another important mechanism by which AXL signaling promotes tumor cell invasion and migration is through the activation of matrix metalloproteinases (MMPs)." (PMID 27834845, 2016). "Together these findings highlight the important role of the tumor microenvironment in the activation of AXL signaling." (PMID 27834845, 2016). "Genetic and therapeutic inhibition of GAS6/AXL signaling has been utilized to identify important functional roles for AXL signaling in tumor progression, metastasis, and drug resistance." (PMID 27834845, 2016). "Future studies are needed to thoroughly investigate the cellular and molecular mechanisms by which AXL signaling promotes tumor progression in order to develop the most effective anti-AXL combination therapies." (PMID 27834845, 2016). "The receptor tyrosine kinase AXL has been identified as a novel therapeutic target given its involvement in tumor invasion and migration." (PMID 27764792, 2016). "Collectively, these data suggest that the interaction between M2 TAMs and TNBC cells through AXL has an important role in supporting tumor progression and chemoresistance." (PMID 28721387, 2016). "Recent studies have revealed a central role of AXL signaling in tumor proliferation, survival, stem cell phenotype, metastasis, and resistance to cancer therapy." (PMID 27834845, 2016). "That is, both AXL expression alone and also AXL co-expression with HER2 were associated with increased risk of death and tumor recurrence in patients with ESCC." (PMID 27172793, 2016). "Reciprocal colony growth is dependent on SHH activation of PSCs and IGF1R/AXL-AKT activity in tumor cells." (PMID 27087446, 2016). "Overall, our data provide support for the use of AXL targeted therapy to reduce tumor aggressiveness, overcome chemotherapy resistance, and impair the cross-talk between cancer cells and TAMs, in patients with TNBC overexpressing AXL." (PMID 28721387, 2016). "While AXL is rarely mutated in human cancers, the majority of tumors overexpress AXL during tumor progression and/or drug treatment to promote progression, metastasis and resistance." (PMID 27834845, 2016). "In preclinical studies, genetic inactivation of AXL is sufficient to decrease the migratory, invasive and metastatic potential of tumor cells." (PMID 27834845, 2016). "Combined IGF1R and AXL inhibitors are required to block the PSC-induced tumor cell phosphoproteome—suggesting a Boolean “OR” axis between PSC IGF1/GAS6 and PDA pAKT." (PMID 27087446, 2016). "Stress conditions within the tumor microenvironment play an important role in the activation of GAS6/AXL signaling." (PMID 27834845, 2016).
tumor (continued). "Given the plasticity and heterogeneity of macrophages, we next investigated the role of AXL in shaping the inflammatory tumor microenvironment in TNBC." (PMID 28721387, 2016). "The mechanisms by which AXL inhibition exerts anti-tumor effects are similar to those described for MERTK inhibition in AML and ALL." (PMID 27834816, 2016). "Overall, we found a continuous increase of AXL expression during tumor progression with significantly higher levels in malignant specimens compared to normal mucosa (p < 0.001)." (PMID 28025482, 2016). "Genetic and pharmacologic inhibition of GAS6/AXL signaling in tumor models has begun to illuminate the diverse mechanisms by which this signaling pathway promotes tumor progression and drug resistance." (PMID 27834845, 2016). "As IGF1 and GAS6 are secreted by activated PSCs, we investigated the dependency of IGF1R and AXL activity on the PSC-induced tumor cell phosphoproteome." (PMID 27087446, 2016). "Research over the past decade has focused on elucidating the functional role of GAS6/AXL signaling within the tumor microenvironment as well as determining the molecular mechanisms by which GAS6/AXL signaling promotes tumor progression." (PMID 27834845, 2016). "The majority of work in the field has focused on the role of AXL signaling in tumor cells and its impact on tumor behavior." (PMID 27834845, 2016). "Due to the nature of our cohort, we were, moreover, able to confirm the increased AXL expression in matched primary tumor and lymph node metastases specimens from the same patient." (PMID 28025482, 2016). "To further investigate the ability of AXL-expressing TNBC cells to promote macrophage polarization towards a pro-tumor phenotype, we analyzed the expression of the M2 specific markers CD206 and CD163 by flow cytometry." (PMID 28721387, 2016). "In cancer, GAS6/AXL signaling can be activated in an autocrine or paracrine manner with tumor cells as well as cells within the tumor microenvironment, including macrophages and endothelial cells producing biologically relevant sources of GAS6." (PMID 27834845, 2016). "Together, these studies implicate GAS6/AXL signaling as an important pathway driving tumor growth, metastasis, and drug resistance." (PMID 27834845, 2016). "This line of reasoning led us to investigate the relationship between GAS6 expression, which would be expected to impact signaling through both MERTK and AXL, and tumor progression in GBM using the TCGA database." (PMID 27783662, 2016). "Future studies investigating the role of AXL signaling within individual stromal cell populations are needed to better understand the diverse roles of GAS6/AXL signaling within the tumor microenvironment." (PMID 27834845, 2016). "In tumor cells, AXL over-expression promotes migration and invasion, whereas AXL inhibition decreases cell invasion and increases chemosensitivity." (PMID 27764792, 2016). "Immunohistochemical staining of tumor tissues has shown that AXL, GAS6 and HIF-1 are coexpressed, supporting the concept that hypoxia and HIF activity is a mechanism for AXL upregulation in human cancers." (PMID 27834845, 2016). "Studies over the past decade have revealed that AXL is a key factor upregulated by tumor cells to promote resistance to multiple anti-cancer strategies." (PMID 27834845, 2016). "To check the heterogeneous status of AXL expression, we independently analyzed two cores for each tumor specimen, and adopted the higher score, as described in Methods." (PMID 27100677, 2016). "While these findings indicate an important role for TAM signaling in anti-tumor responses mediated by NK cells, future studies are needed to determine the specific and relative contributions of AXL, TYRO3, and MER to NK cell antitumor activities." (PMID 27834845, 2016). "Collectively, these results reveal activated stromal cells can return a differential signal to tumor cells via an IGF1R/AXL-AKT axis." (PMID 27087446, 2016).